SLC25A18 (solute carrier family 25 member 18)
Description:
Responsible for the transport of glutamate from the cytosol into the mitochondrial matrix with the concomitant import of a proton (symport system).
Synonyms: GC2
Tractability: Antibody: UniProt predicts a signal peptide or a membrane-spanning region. PROTAC: ubiquitination databases record sites on it; its protein half-life has been measured.
Gene: Protein-coding gene on chromosome 22 (17,563,086 to 17,591,909, forward strand). Ensembl gene ENSG00000182902.
Subcellular location: Mitochondrion inner membrane
Subcellular location (Human Protein Atlas): Mitochondria; Nucleoplasm
Pathways (Reactome):
Metabolism: Malate-aspartate shuttle
Transport of small molecules: SLC-mediated transport of neurotransmitters
Gene Ontology:
Molecular function: amino acid:proton symporter activity; protein binding; L-aspartate transmembrane transporter activity; L-glutamate transmembrane transporter activity
Biological process: L-glutamate transmembrane transport; aspartate transmembrane transport; malate-aspartate shuttle; neurotransmitter transport; L-aspartate transmembrane transport; proton transmembrane transport; transmembrane transport
Cellular component: mitochondrion; mitochondrial inner membrane
Genetic constraint (gnomAD): Loss-of-function variants: 29 observed, 34.74 expected, observed/expected ratio (o/e) 0.83, 90% interval 0.62 to 1.14. The upper end of that interval is the gene's LOEUF score, 1.14, which puts it in group 4 of 6, group 1 being the genes least tolerant of losing a copy. Missense variants: 371 observed, 424.64 expected, observed/expected ratio (o/e) 0.87, 90% interval 0.8 to 0.95. Synonymous variants: 173 observed, 160.37 expected, observed/expected ratio (o/e) 1.08, 90% interval 0.95 to 1.22.
Homologues: Orthologues: chimpanzee SLC25A18 (99% identical), macaque SLC25A18 (95% identical), dog SLC25A18 (89% identical), mouse Slc25a18 (88% identical), rat Slc25a18 (86% identical), guinea pig SLC25A18 (83% identical), tropical clawed frog slc25a18 (71% identical). Paralogues in human: SLC25A22 (65% identical), SLC25A12 (30% identical), SLC25A13 (30% identical), SLC25A1 (28% identical), SLC25A21 (27% identical), SLC25A26 (27% identical), SLC25A37 (26% identical), SLC25A20 (26% identical), SLC25A39 (26% identical), SLC25A10 (25% identical), SLC25A40 (25% identical), SLC25A45 (25% identical), and 37 more.
Diseases named in the same sentence as SLC25A18 in open-access papers:
SLC25A18 is named in the same sentence as 36 diseases in open-access papers, as found by Europe PMC text mining. Sharing a sentence is not in itself a finding about the gene and the disease. The quoted sentences say what the papers report.
glioma (2 papers, 2022 to 2025). A benign or malignant brain and spinal cord tumor that arises from glial cells (astrocytes, oligodendrocytes, ependymal cells). "SLC25A18, another key marker, showed the highest expression levels in lower-grade gliomas (WHO grade II) with IDH mutation and in IDH-mutant, 1p19q co-deleted (LGG) subtypes." (PMID 40018519, 2025). "This expression pattern aligns with the less aggressive clinical behavior typically observed in these glioma subtypes and highlights SLC25A18’s potential involvement in the metabolic adaptations associated with IDH mutations." (PMID 40018519, 2025).
congenital heart disease (1 paper, 2023). A heart disease that is present at birth. "Among these genes, amplification of the genes CECR2, SLC25A18 and ATP6V1E1, mapping within the critical region for CES, may be responsible for iris coloboma,congenital heart disease, craniofacial anomalies in patients with CES." (PMID 37880750, 2023).
tumor (4 papers, 2015 to 2025). "Our models demonstrated that EFHD1 and SLC25A18 were significantly associated with the cell cycle (R2 = 0.790), while SASH1 and FAM110B showed a notable association with tumor stemness (R2 = 0.522)." (PMID 40018519, 2025). "Notably, EFHD1 and SLC25A18 exhibited strong positive correlations with cellular processes related to the cell cycle (Cor = 0.368/0.385, P < =0.001), whereas SASH1 and FAM110B were found to be closely associated with tumor stemness (Cor =0.328/0.427, P < =0.001)." (PMID 40018519, 2025).
mitochondrial disease (1 paper, 2025). "The identification of mitochondrial disease-specific markers (EFHD1, SASH1, FAM110B, and SLC25A18) highlights shared mechanisms, such as oxidative phosphorylation, calcium signaling, and immune responses, that can serve as therapeutic targets in both AD and GBM." (PMID 40018519, 2025).
SLC25A18 also shares sentences with these, for which no sentence is quoted: cancer (5 papers); asthma (4); genital herpes (4); gastric cancer (3); bladder cancer (2); breast carcinoma (2); Hypertension (2); lung carcinoma (2); adenocarcinoma (1); asthenozoospermia (1); bronchiectasis (1); chronic obstructive pulmonary disease (1); citrullinemia (1); colorectal adenoma (1); colorectal cancer (1); cyst (1); dementia (1); emphysema (1); inflammatory bowel disease (1); iris coloboma (1); latent infection (1); Leber congenital amaurosis (1); musculoskeletal disorders (1); myocarditis (1); oral squamous cell carcinoma (1); osteopetrosis (1); osteoporosis (1); osteosarcoma (1); ovarian serous adenocarcinoma (1); prostate carcinoma (1).
A further 2 diseases each share a sentence with SLC25A18 in 1 paper.